TNF (tumor necrosis factor)
Diseases named in the same sentence as TNF in open-access papers (continued):
Sharing a sentence is not in itself a finding about the gene and the disease.
leukocytosis (continued). "In a typical inflammatory response model, interleukin-6 (IL-6) and tumor necrosis factor-alpha (TNF-α) are produced first, followed by an increase in interleukin-2 (IL-2) and interleukin-1α (IL-1α), which may lead to leukocytosis due to neutrophilia in the systemic circulation and immunosuppression." (PMID 38918542, 2024). "First, although we had previously reported that a high DII diet before pregnancy is associated with leukocytosis in the first trimester, we did not measure plasma inflammatory markers, such as white blood cell, cytokines, such as CRP, IL-6, and TNFα, at the time of delivery in the present study." (PMID 33202775, 2020). "In conclusion, we showed that mammary ASR, which manifested itself by an intense milk leukocytosis, was characterized by the production of IL-17A and IFN-γ but the absence of detectable TNF-α, with a low and inconsistent presence of IL-1β and IL-6." (PMID 23696826, 2013).
sleep disorder (63 papers, 2010 to 2026). A change from the patient's baseline sleeping pattern, in the hours slept and/or an alteration/dysfunction in the stages of sleep. "Elevated levels of IL-1β and TNF-α have been linked to various sleep disorders, such as sleep apnoea and chronic insomnia." (PMID 40254933, 2025). "This factor is mainly associated with sleep disturbances in patients suffering from conditions characterized by elevated TNF." (PMID 36140260, 2022). "Both short sleep and sleep disturbances are associated with increased levels of pro-inflammatory biomarkers such as interleukin-1 (IL-1), interleukin-6 (IL-6) and tumor necrosis factor (TNF)." (PMID 33042933, 2020). "Similarly, sleep disturbances are associated with reduced growth hormone production and elevated levels of inflammatory cytokines, such as IL-6 and TNF-α, which contribute to poor wound healing outcomes." (PMID 40687576, 2025). "For BMI, studies have showed that an increase of 6 units BMI can resulted in four time greater risk of OSA, specifically, The disruption of pro-inflammatory factors (e.g., IL-6, IL-12, TNF-α) caused by excessive visceral fat has been identified as a significant risk factor for sleep disorders." (PMID 40034171, 2025). "Indeed, it was observed that obese subjects had higher levels of IL-6 and TNF-α during the morning vs. the night, which was associated with sleep disorders and BMI." (PMID 39716153, 2024). "It remarkably decreased the levels of TNF-α, which is linked to sleep disorders." (PMID 38750102, 2024). "Moreover, sleep disorders impair the immune response and cause systemic inflammation by the dysregulation of substances such as TNF-α, IL-1β, and IL-6." (PMID 36188174, 2022). "Sleep disorders are also associated with an increased systemic immune and inflammatory dysregulation, mainly due to hyperexpression of pro-inflammatory mediators and cytokines (e.g., IL-1β, IL-2, IL-6, TNF-α, IL-18, sTNF-R1, and sTNF-R2), and intermittent hypoxia-induced oxidative stress." (PMID 41156291, 2025). "Thus, itcan be seen that sleep disorders can significantly impact immune system functionsince sleep deprivation is directly associated with an increase in pro-inflammatorycytokines, such as IL-6 and TNF-α, and a decrease in circulating killercells." (PMID 36158715, 2022). "Thus, our data indicate that the IL-1β-31TT genotype and the APOEε4 allele were associated with sleep disturbances in AD patients and that these two SNPs synergistically enhanced LPS-induced IL-1β, IL-6 and TNF-α overexpression in white blood cells from AD patients with sleep disturbances." (PMID 26937653, 2016). "Increase levels of inflammatory mediators such as Interleukin-6 and Tumor Necrosis Factor-alpha have also been shown in patients with sleep disorders." (PMID 40710903, 2025). "Sleep disorders further exacerbate healing delays by disrupting growth hormone secretion and increasing the release of inflammatory cytokines (e.g., IL-6, TNF-α)." (PMID 40687576, 2025). "Inflammatory cytokines such as IL-1β, IL-6, and TNF-α, which are elevated in both sleep disorders and cancer, play a critical role in immune dysregulation." (PMID 39120277, 2024). "In the acute phase of cerebral ischemia, the proliferation and activation of microglia led to a robust inflammatory response, characterized by increased levels of TNF and IL-1β and upregulation of IL-6, which can result in sleep disorders." (PMID 38671959, 2024). "Remarkably, continuous positive airway pressure (CPAP) treatment demonstrates the capacity to normalize TNF values in OSAS individuals, suggesting a potential avenue for mitigating the inflammatory impact associated with this sleep disorder." (PMID 38672697, 2024). "Multiple studies in individuals with MDD have demonstrated that sleep disturbances were associated with higher levels of circulating C-reactive protein (CRP), serum tumour necrosis factor (TNF) α, interleukin(IL)−6, interferon(IFN)-α2, and IFN-γ." (PMID 37176140, 2023).
sleep disorder (continued). "Acupuncture was also reported to improve sleep disorders in PTSD insomnia rats by increasing the TNF content of the hypothalamus and decreasing IL4 expression." (PMID 37200784, 2023). "Several studies reported that IL-6 and TNF-α significantly increase in patients with sleep disorders." (PMID 36570021, 2022). "Increased gut microbiota-derived lipopolysaccharide (LPS) contributes to the production of proinflammatory cytokines such as IL-1β, TNF-α, and IL-6, which have been shown to play a key role in sleep disturbances." (PMID 36190400, 2022). "In this study, the concentrations of IL-6, TNF-α, and IL-10 were monitored before and after operation in patients with sleep disorders at different time points, to observe the relationship between sleep disorders and the level of cytokines." (PMID 36570021, 2022). "In the present study, we found increased TNFα levels in adolescents with MDD who displayed sleep disturbances." (PMID 33192676, 2020). "Sleep disorders promote a low-grade inflammatory status by increasing circulating proinflammatory cytokines (IL-1β, IL-6, IL-17A, TNF-α) and CRP." (PMID 30402295, 2018). "Studies have found that patients with sleep disturbance show altered circulating concentrations of TNF-α, IL-1β, and IL-1." (PMID 21034496, 2010). "Furthermore, TNF-α levels were reported to increase in the gingival crevicular fluid of infants with sleep disorders and fever during tooth eruption." (PMID 40360766, 2026). "Vitamin D may lead to sleep disorders by decreasing the release of inflammatory mediators such as tumour necrosis factor-alpha (TNF-α) and prostaglandin D2." (PMID 40506917, 2025). "The increase in pro-inflammatory cytokines including interleukin (IL)-1, IL-6, IL-8, IL-17 and tumor necrosis factor, in turn, may affect the brain and contribute to the etiopathogenesis of sleep disorders." (PMID 39396146, 2024). "On the other hand, several studies show how sleep disorders can lead to higher levels of different inflammatory and autoimmune markers in humans, such as higher levels of C-Reactive Protein, Interleucin-6 or Tumor Necrosis Factor." (PMID 36834203, 2023). "Notably, IL-6 and TNF are key molecules in the interactions between sleep and neuroinflammation and have been found to be elevated also in several sleep disorders." (PMID 37465321, 2023). "These bidirectional associations could be equally mediated by proteins, such as BDNF (brain-derived neurotrophic factors) or proinflammatory cytokines (IL-1β, TNF-α), which are involved in both pain perception and sleep disorders." (PMID 34574901, 2021). "In fact, an increased level of TNFα has been reported in the serum of PD patients (HY score 2; corresponding to 12 h in our model), and correlating with the cognitive and mood decline, sleep disorder, as well as correlating with the Hoehn & Yahr progression." (PMID 31064126, 2019). "For instance, lower 25(OH)D levels might lead to sleep disorders through affecting sleep regulating substance, such as melatonin, tumor necrosis factor alpha (TNF-α), interleukin-1 (IL-1) and prostaglandin D2 (PD2)." (PMID 30081486, 2018). "In addition, both IL-1 (α and β) and TNF-α are present in a variety of clinical conditions involving sleep disorders, such as chronic insomnia and OSA." (PMID 24367384, 2013). "Certain cytokines, including IL-6, IL-1α, and tumor necrosis factor (TNF-α), exhibit notable circadian oscillations when they enter the brain, leading to sleep disorders." (PMID 39418274, 2024). "Patients with sleep disorders due to acute cerebral infarction displayed increased inflammatory factors, including C-reactive protein (CRP), IL-6, IL-1β, TNF-α and Hcrt, compared with normal levels." (PMID 38671959, 2024). "Increasing evidence has shown that elevated levels of inflammatory cytokines like IL-6 and TNFα were found in adults with MDD and people with sleep disorders." (PMID 37034932, 2023).
sleep disorder (continued). "Effectively, IL1-β and TNF-α, which increase in the serum of animals in OSA models and in that of patients with this sleep disorder, have proved to increase the adhesion of MSC to cardiac endothelial cells both in vivo and in vitro." (PMID 20604943, 2010). "EDS, the cardinal symptom of OSAS, may be mediated by cytokines, and EDS patients with sleep disorders such as OSAS, narcolepsy, and idiopathic hypersomnia often have high levels of IL-6 and TNF-α cytokines." (PMID 24895539, 2014). "For instance, methotrexate may improve sleep disorders in RA patients but not as effectively as etanercept (an anti-TNF-alpha inhibitor)." (PMID 38999222, 2024). "However, in RA patients with sleep disturbances (assessed with questionnaires), the anti-TNF-α therapy did not ameliorate sleep disturbances." (PMID 36140260, 2022).
alcoholic hepatitis (62 papers, 1997 to 2025). Acute hepatitis resulting from ingestion of alcohol. "It has been demonstrated that high level of TNF-α in serum is associated with the pathophysiology of alcoholic hepatitis patients." (PMID 35620283, 2022). "TNF-α increased in both the circulation and liver of alcoholic hepatitis and have been shown to be associated with disease severity." (PMID 34321090, 2021). "In particular, alcohol-induced ROS activates NF-κB signaling pathway which, in turn, stimulates TNF-α production that is associated with progression of alcoholic hepatitis." (PMID 29176803, 2017). "Highly elevated TNFα levels in the blood, in turn, are associated with poorer outcomes in patients with acute alcoholic hepatitis." (PMID 26717583, 2015). "Additionally, the expression of TNFα receptors and the spontaneous secretion of TNFα from circulating monocytes isolated from ALD patients and the association of high serum TNFα with poorer prognosis of acute alcoholic hepatitis patients all further suggests the critical role of monocytes in ALD." (PMID 33995391, 2021). "However, it is also important to note that TNFα plays a key role in hepatocyte regeneration and promotes hepatic infiltration by immune cells which drive repair or fight sepsis which is a significant risk in alcoholic hepatitis." (PMID 35095549, 2021). "In patients with alcoholic hepatitis, there were observed increasing levels of TNF-α, IL-6, IL-8, and IL-18 pro-inflammatory cytokines." (PMID 38473721, 2024). "Corticosteroid and TNF-α inhibitors are tested for the treatment of alcoholic hepatitis but the results are controversial as both the molecules inhibit liver regeneration and enhance the rate of bacterial infection." (PMID 38146363, 2023). "Targeting systemic inflammation through tumor necrosis factor α (TNFα) inhibition has been studied in patients with alcoholic hepatitis." (PMID 38101419, 2023). "Elevated TNF levels in alcoholic hepatitis patients play a crucial rolein mediating hepatocyte damage and correlate inversely with patient survival." (PMID 36518124, 2022). "The concept of TLR4 activation with subsequent TNF-α release has conducted to translational approaches such as the anti-TNF-α therapies for patients with severe alcoholic hepatitis." (PMID 34884492, 2021). "As an example, antibodies against TNF were tested as potential anti-inflammatory therapies in human alcoholic hepatitis but some studies were terminated due to adverse outcomes or showed no mortality benefit over standard therapies." (PMID 35095549, 2021). "Serum TNF-α levels are elevated in ALD, especially in alcoholic hepatitis, and the use of infliximab and etanercept, TNF-α inhibitors, increased mortality in these patients; therefore, PTX appeared useful in preventing HRS in sAH patients." (PMID 34820395, 2021). "Animal models of ALD and patients with alcoholic hepatitis showed an increase in the TNF-α, IL-1, and IL-6 levels." (PMID 32423176, 2020). "In response to the pro-inflammatory mediator TNFα, alcoholic hepatitis patients fail to raise sCD18 equivalent to that of healthy subjects." (PMID 29904132, 2018). "Treatment for severe alcoholic hepatitis includes administration of corticosteroids, pentoxifylline, anti-TNF-α antibody, and plasma exchange and hemodialysis, but the efficacy is unclear." (PMID 28403148, 2017). "In peripheral blood monocytes isolated from patients with alcoholic hepatitis, expression of TNFα mRNA was robustly increased in response to challenge with lipopolysaccharide." (PMID 29142263, 2017). "In patients with acute alcoholic hepatitis, TNFα levels in subcutaneous adipose tissue were a stronger indicator of liver injury and systemic inflammation than TNFα produced by the liver." (PMID 28212318, 2017). "The plasma concentrations of inflammatory cytokines such as TNF-α, IL-1, IL-6 and IL-8 are high in patients with alcoholic hepatitis." (PMID 28403148, 2017).
alcoholic hepatitis (continued). "Among the mediators identified, the cytokine TNFα has been extensively studied not only in patients with alcoholic hepatitis but also in animal models of ALD." (PMID 26717583, 2015). "Clinical studies have shown that the plasma endotoxin and hepatic cytokines including TNF-α, IL-6, and IL-8 were increased in patients with alcoholic hepatitis, while declined in the recovery phase." (PMID 26501337, 2015). "Recently, PTX, with combined anti-inflammatory (TNF-α inhibition) and antifibrogenic properties, has been found to be useful in patients with acute alcoholic hepatitis." (PMID 24106597, 2013). "Pentoxifylline, a tumor necrosis factor alpha (TNFα) suppressor, and infliximab, an anti-TNFα mouse/human chimeric antibody, has been extensively studied in patients with alcoholic hepatitis." (PMID 21994849, 2011). "They found that peripheral blood monocytes from patients who had alcoholic hepatitis have spontaneous TNF production and enhanced LPS-stimulated TNF production." (PMID 20221393, 2010). "While the role of TNF-α in the development of ALD has been well characterized, clinical investigations of the therapeutic efficacy of antibodies to TNF-α (e.g., infliximab) to treat patients with acute alcoholic hepatitis have generated variable results." (PMID 20827314, 2010). "The concentrations in the blood of TNF–α and the other inflammatory cytokines were increased in patients with alcoholic hepatitis." (PMID 15540802, 2003). "Taken together, these findings indicate how important intestinally derived endotoxin and endotoxin-induced cytokines, such as TNF–α, are to the development of alcoholic hepatitis." (PMID 15540802, 2003). "Patients with alcoholic hepatitis frequently have high levels of cytokines in their bloodstream, including tumor necrosis factor alpha (TNF-α)." (PMID 15706758, 1997). "Several studies have found that TNF-α levels were elevated in patients with alcoholic hepatitis and in rats with alcohol-induced liver injury." (PMID 15706744, 1997). "Therapeutic measures for patients with alcoholic hepatitis of varying severity, in addition to alcohol abstinence and optimal nutrition, include corticosteroids, pentoxifylline, anti-tumor necrosis factor (anti-TNF) agents, and extracorporeal liver support." (PMID 39600547, 2024). "Additionally, it has been reported that both TNF-α and IL-6 are substantially elevated in the circulation of patients with acute alcoholic hepatitis." (PMID 36144575, 2022). "LPS-induced TNF-α expression in KCs plays a key role in alcoholic hepatitis and ALD." (PMID 36145643, 2022). "In alcoholic hepatitis, TNFα/IFNγ induces FAT10 expression via NFκB and/or STAT3 pathways." (PMID 32630199, 2020). "Although innate immunity is considered to play a central role, increasing studies have also reported that cytotoxic T cells and T helper cells infiltrate into the liver in alcoholic hepatitis and active alcoholic cirrhosis, thus leading to the production of pro-inflammatory cytokines like TNF-α." (PMID 30072984, 2018). "However, the TNFα-mediated enhancement of CD18 shedding per monocytes was lower in alcoholic hepatitis patients than in healthy controls (p < 0.05)." (PMID 29904132, 2018). "TNF alpha-induced inflammation is more prevalent in alcoholic hepatitis." (PMID 22518321, 2012). "A recent study indicated that cytokines such as tumor necrosis factor-alpha and interleukin-10 in adipose tissues of acute alcoholic hepatitis patients were elevated, and were correlated with the serum CRP concentration, implying that inflammation caused the production of CRP." (PMID 21806828, 2011). "In the MOD group, intervention with COST and COSM led to a reduction in serum levels of the inflammatory cytokines TNF-α, IL-1β, and IL-6 in the mice, suggesting that both compounds may ameliorate alcoholic hepatitis, albeit with COSM exhibiting slightly superior efficacy compared to COST." (PMID 40137320, 2025).
alcoholic hepatitis (continued). "Moreover, increased TNF alpha was found in patients with alcoholic hepatitis." (PMID 22518321, 2012). "In summary, FAT10 was only found in human and mouse liver specimens and plays critical role in the development of alcoholic hepatitis via NFκB and/or STAT3 pathways induced by TNFα/IFNγ." (PMID 32630199, 2020). "The pathway that increases FAT10 expression includes TNFα and IFNγ, followed by NFκB and STAT3, all of which were up-regulated in alcoholic hepatitis." (PMID 32630199, 2020). "TNFα and LPS was able to increase the shedding of CD18 per monocyte and the total sCD18 level both in alcoholic hepatitis and in healthy controls (p < 0.05)." (PMID 29904132, 2018). "Serum level of cytokines such as tumor necrosis factor (TNF)-α, interleukin (IL)-1, IL-6 and IL-8 are elevated in acute alcoholic hepatitis." (PMID 24106597, 2013). "High serum levels of TNF-α and TNF-R1 correlated with mortality in patients with acute alcoholic hepatitis." (PMID 20827314, 2010). "Pentoxifylline has been known as a selective inhibitor of TNF-α and has been used in treating patients with severe alcoholic hepatitis in a randomized study, but it did not improve outcomes." (PMID 36160411, 2022). "TNF-α, an inflammatory cytokine, has been reported to be a hinge in alcoholic liver injury, and the circulating level of TNF-α correlates with the severity of alcoholic hepatitis and alcoholic hepatitis mortality." (PMID 33716743, 2021). "It is worthy to note that patients with severe alcoholic hepatitis who do not respond to medical treatment have low hepatic expression of TNF and IL-61." (PMID 30237578, 2018). "Patients with severe alcoholic hepatitis who do not respond to corticosteroids can use pentoxifylline, a tumor necrosis factor (TNF)-α inhibitor, although there could be harmful side effects." (PMID 40430529, 2025). "Because TNF-α is produced predominantly by the monocyte macrophage lineage and the major population of this lineage in the liver is Kupffer cells, increased production of TNF-α by activated Kupffer cells may be responsible for alcoholic hepatitis." (PMID 24090365, 2013).